MSTN (myostatin)
Diseases named in the same sentence as MSTN in open-access papers (continued):
Sharing a sentence is not in itself a finding about the gene and the disease.
cancer (continued). "Evidence from studies performed in mouse models of cancer cachexia has demonstrated that the blockade of myostatin and activin receptors prevents muscle wasting." (PMID 36078078, 2022). "While in patients with cancer cachexia, myostatin concentration was found to be positively correlated with muscle index, muscle density and muscle strength in a cross-sectional study." (PMID 36330524, 2022). "MSTN levels and MSTN-mediated signaling pathways were found to be upregulated in experimental cancer cachexia and cancer patients even before the development of cancer cachexia." (PMID 35812316, 2022). "Hepatic alterations have been associated with cancer-induced muscle wasting and furthermore liver fibrosis-induced muscle atrophy was promoted by elevated levels of circulating IL-6, TNF-α and myostatin during progression of liver disease." (PMID 35994202, 2022). "Unfortunately, the side effects documented in healthy adult individuals, boys with Duchenne muscular dystrophy and cancer patients limited attempts to reduce activin A and myostatin signaling in humans." (PMID 36078078, 2022). "Among the most extensively employed preclinical murine cancer cachexia models, the Colon 26 (C26) adenocarcinomas were reported to have markedly higher gene expression levels of activin A and myostatin when compared to Lewis lung carcinoma (LLC) tumors." (PMID 33671024, 2021). "Several drugs, including megestrol acetate, ghrelin agonists, and anti-myostatin peptides, are expected to improve cancer cachexia, in addition to nutritional support and physical exercise." (PMID 34473762, 2021). "In cancer cachexia, signaling pathways other than the myostatin/activin A pathway have been investigated." (PMID 32605273, 2020). "In particular, the myostatin/activin A signaling pathway plays a significant role in cancer-induced muscle atrophy." (PMID 32605273, 2020). "KEGG pathway enrichment revealed remarkable involvement of myostatin in pathways including metabolic pathways, ribosomes, pathways in cancer, and the PI3K-Akt signaling pathway." (PMID 33536903, 2020). "TGF-β and myostatin, which are upregulated in cancer patients, downregulate miR-206 and MyoD levels in skeletal muscle." (PMID 31941005, 2020). "At the same time, myostatin has been found related to increased muscle wasting during cancer, representing a possible target against CC." (PMID 33255345, 2020). "Tumor cell-derived mediators such as TNFα, IL-6, TWEAK, myostatin and extracellular vesicle HSPs have been postulated to play a role in the pathogenesis of cancer cachexia." (PMID 31851697, 2019). "Cancer mediated myotube atrophy is known to be induced by several catabolic mediators, such as E3 ubiquitin ligases, NF-κB, and myostatin." (PMID 31717643, 2019). "Currently in clinical trials, applying monoclonal antibodies that bind to myostatin to inhibit its function is a potential therapy to treat cachexia syndrome in cancer patients (Nicole, Lisa, Wolfram, Anker, & Stephan, 2014)." (PMID 30859746, 2019). "Ubiquitin-mediated proteolysis activated by MSTN is one of the mechanisms by which cancer cachexia leads to muscle atrophy." (PMID 30922397, 2019). "Overproduction of myostatin and activin A observed in the atrophying muscle of the cancer-alone and CGC groups was significantly decreased in the mice in the CGCA group." (PMID 29731967, 2018). "For example, in cancer cachexia, activated STAT3 has been shown to initiate skeletal muscle protein loss via the stimulation of caspases, myostatin and the ubiquitin-proteasome system." (PMID 29897957, 2018). "CDD866 (murinized version of bimagrumab) is a neutralizing antibody against the activin receptor type II (ActRII) preventing binding of ligands such as myostatin and activin A, which are involved in cancer cachexia." (PMID 27462398, 2016).
cancer (continued). "Recently myostatin was identified in the secretome of C26 colon cancer cells and experimentally confirmed as novel tumoral factor that induces cancer cachexia via binding to ACVR2B." (PMID 27330885, 2016). "Studies investigating the relevance of myostatin or ActRIIB signaling in human cancer patients are scarce." (PMID 26856534, 2016). "In a murine model of cancer cachexia, inhibition of myostatin by specific antibodies was able to attenuate the atrophy of skeletal muscle and improved muscle mass and function." (PMID 26856534, 2016). "Overproduction of myostatin and activin A is often seen in cancer patients suffering from cachexia and experimental cancer cachexia models." (PMID 27323407, 2016). "It has recently been shown that myostatin is also secreted by C26 carcinoma cells and other murine and human neoplasms." (PMID 26856534, 2016). "The authors suggested that myostatin secretion by cachexia-inducing neoplasm would initiate the pathogenesis of cancer cachexia." (PMID 26508818, 2015). "Myostatin promotes skeletal muscle wasting in different catabolic conditions, including cancer and it has been shown to be secreted by cancer cells." (PMID 26668061, 2015). "Many factors have been implicated in cancer cachexia including cytokines (TNFα, IL-6), ZAG and myostatin." (PMID 24667661, 2014). "Studies have investigated the therapeutic potential of inhibiting myostatin and ActRIIB in treating cancer cachexia." (PMID 24624094, 2014). "Two recent papers have reported the beneficial effects of blocking the myostatin/activin signalling pathway in mouse models of cancer cachexia." (PMID 21798080, 2011). "LJFE ameliorated muscle atrophy in the cancer cachexia model by inhibiting MSTN." (PMID 40672545, 2025). "Therefore, myostatin‐inhibitory interventions have been proposed as a potential therapeutic strategy to ameliorate CAC in patients with cancer." (PMID 40810552, 2025). "This study examined whether water and ethanol extracts of L. japonica fruit could improve cancer cachexia, focusing on the effects of the extracts on MSTN activity using both in vivo and in vitro models." (PMID 40672545, 2025). "In addition to myostatin, many cancers secrete activin A, a closely related TGF-β family ligand that uses the same ActRIIB receptor." (PMID 40869331, 2025). "Given these research findings, the implementation of myostatin inhibitor strategy aimed at reducing myostatin levels may hold promise for enhancing muscle mass in those with cancer-induced muscle wasting." (PMID 37755304, 2023). "Interestingly, other markers like ghrelin and myostatin remained stable, further implicating IL‐6 and NF‐κB signaling as key mediators of cancer cachexia." (PMID 37533407, 2023). "Although investigating myostatin as a potential avenue for intervening in the preservation of muscle mass in cancer cachexia holds promise, its translation to human applications remains uncertain due to the lack of specificity and potential toxicities in clinical patients." (PMID 37755304, 2023). "One example specific for cancer cachexia is the anti-myostatin antibody landogrozumab, which progressed to a Phase II trial in pancreatic cancer patients; although, it was not considered to be superior to placebo in improving outcome measures related to muscle wasting." (PMID 36078078, 2022). "Furthermore, STAT3 phosphorylation leads to the activation of atrogin‐1, MuRF‐1, and MSTN in cancer patients with cachexia." (PMID 36127129, 2022). "In addition, muscle hypertrophy and cancer cells show increased IGF-AKT1-mTORC1 or reduced myostatin signaling." (PMID 35326510, 2022). "In line with the findings of the animal studies, results of clinical trials administering anti-myostatin antibodies revealed increased muscle volume and lean mass in sarcopenic cancer patients without causing major side effects." (PMID 35454797, 2022).
cancer (continued). "Both Myostatin and Activin-A share a common receptor: activin-type-2-receptor B. Its antagonism represents another potential therapeutic target for cancer cachexia, with reversed muscle wasting and prolonged survival noted in cancer cachexia murine models treated in such a fashion." (PMID 36269458, 2022). "Another mediator for cancer cachexia is myostatin, a TGF-β family member." (PMID 36078078, 2022). "Acting through the same receptor than MSTN (ActRIIB), Activin A is also found to be increased in cancer cachexia and an independent prognosis factor of survival in cancer patients." (PMID 34595171, 2021). "As myostatin inhibition has been utilized to examine various physiological processes other than merely muscular regeneration (including cancer survival, bone- and energy metabolism), the following will focus on the bulk of scientific work that describes the effect of myostatin on muscular tissue." (PMID 33802348, 2021). "Previous studies have reported that myostatin expression is significantly increased in different human cancer tissues and cells, and that myostatin knockdown increases cancer cell apoptosis via modulation of mitochondrial metabolism and reactive oxygen species." (PMID 33198216, 2020). "Thus, miR-486 is an integral part of the myogenesis signaling network that involves Pax7, MyoD, myostatin, and NF-κB and a potential target of cancer-induced chemokines/cytokines." (PMID 31941005, 2020). "Several observations report the causal involvement of other TGFβ family members such as activins, and on the basis of these findings, drugs able to interfere with the activin receptor, which is also shared by myostatin, are currently under investigation as potential tools to manage cancer cachexia." (PMID 30833900, 2019). "Therefore, we supposed that the development of new MSTN inhibitors have potential application values in the treatment of cancer cachexia." (PMID 30922397, 2019). "Although it is controversial whether MSTN is upregulated in patients or animal models with cancer cachexia, it has been accepted that the inhibition of MSTN or its signaling pathway effectively alleviates muscle atrophy and thus relieves cancer cachexia." (PMID 30922397, 2019). "It is potential for MSTN to be a target of anti-cancer cachexia." (PMID 30922397, 2019). "In summary, we tentatively clarify that IMB0901 is a dual MSTN inhibitor simultaneously inhibiting the MSTN promoter activity and the MSTN signaling pathway, thereby protecting muscle atrophy induced by cancer cachexia by inhibiting ubiquitin-mediated proteolysis and promoting protein synthesis." (PMID 30922397, 2019). "The results obtained in the current study are promising and contribute to a growing body of evidence which suggests that muscle wasting in cancer cachexia might be limited by blocking the myostatin signalling pathway." (PMID 31285507, 2019). "However, it has been confirmed that the inhibition of MSTN can inhibit muscle atrophy induced by cancer cachexia." (PMID 30922397, 2019). "Additionally, treatment of cancer cells with myostatin promoted VDAC1 upregulation combined with downregulation and mitochondrial dissociation of HK." (PMID 30576325, 2018). "Moreover, increased TNF-α and myostatin concentrations are often detected in tumor-bearing animals and cancer cachexic patents." (PMID 29069832, 2017). "Myostatin expression is upregulated in experimental models of cancer cachexia." (PMID 26508818, 2015). "BYM338 is a myostatin inhibitor developed by Novartis (Hanover, NJ, USA) to treat cancer cachexia." (PMID 24624094, 2014). "Notably elevated myostatin expression is correlated with muscle wasting in cancer cachexia, heart failure, HIV, CKD, chronic obstructive pulmonary disease, and aging." (PMID 24474938, 2013). "Furthermore, acute inhibition of myostatin/ACVR2B signaling with the antagonist ACVR2B-Fc preserves skeletal muscle in mouse models of cancer cachexia." (PMID 21486491, 2011).
cancer (continued). "Thus, in cancer cachexia, the total “myostatin signal” driving muscle atrophy may originate from a combination of host-derived myostatin (and activins) and tumor-derived factors." (PMID 40869331, 2025). "Moreover, several studies have indicated that inhibition of myostatin could potentially help preserve skeletal muscle in tumor-bearing animal models as well as in cancer patients." (PMID 37755304, 2023). "In addition to cytokines, other tumor-derived factors are implicated in cancer cachexia such as hormones, metal ions, microRNAs, and members of the TGF-β superfamily including TGF-ß, activin A, growth differentiation factor-11 (GDF-11), and myostatin." (PMID 35994202, 2022). "In addition, preclinical studies showed that myostatin expression was significantly increased in different tumor tissues and could block cancer cell death by regulating mitochondrial metabolism." (PMID 33198216, 2020). "However, 30% HD-CM reversed levels of MHC and myostatin that might come from the decreased release of atrophic factors from cancer cells by 4-HD treatment." (PMID 31658768, 2019). "Myostatin-based signaling was found increased in muscles of Yoshida hepatoma-bearing rats, in C26-bearing mice, and in patients with various malignancies, while in pre-cachectic cancer patients circulating levels of myostatin increased only with certain types of tumors." (PMID 30984014, 2019). "The pharmacological blockade of myostatin/activin pathway via the administration of an anti-myostatin monoclonal antibody that inhibit the binding of myostatin to its receptor ActRIIB/ACVR2B was found to be the most effective treatment for muscle wasting in cancer cachetic patients." (PMID 27330885, 2016). "Myostatin, a member of the TGF-β family, is a negative regulator of muscle growth, making it a promising therapeutic target for cancer cachexia." (PMID 40519290, 2025). "This study demonstrated that Litsea japonica fruit extract (LJFE), especially LJFE‐E (30% ethanol extract), alleviated muscle atrophy by modulating myostatin (MSTN) in vitro and in vivo cancer cachexia models." (PMID 40672545, 2025). "However, plasma levels of MSTN are not always correlated with muscle loss in human cancer patients, and genetic deletion of MSTN or its acute inhibition using trichostatin A or FST does not always have a preventive effect against cancer cachexia in experimental rodents." (PMID 35812316, 2022). "Anamorelin (appetite stimulation), megestrol acetate, eicosapentaenoic acid, phytocannabinoids, targeting MSTN/activin, and molecules targeting proinflammatory cytokines, such as TNF-α and IL-6, are being tested as treatment options for cancer cachexia." (PMID 35565236, 2022). "Of note, our upstream analysis identified several TGF-beta superfamily of proteins such as MSTN, GDF11, GDF15, TGF-β suggesting their important roles in cancer and in cachexia, offering a window for therapeutic interventions." (PMID 33334063, 2020). "Similar to cancer, many of these factors including TNFα, IL-6, IL-1, LIF, activin A, and myostatin activate Akt in skeletal muscle cells while stimulating muscle protein loss." (PMID 31480237, 2019). "When connecting clinical deficits and genes, we identified five clusters that give insights into the biology of frailty: cancer, glucocorticoid receptor, TNF-α, myostatin, angiotensin converter enzyme, ApoE, interleukine-12 and −18." (PMID 31332237, 2019). "In three cellular muscle atrophy models with C2C12 myoblasts damaged by dexamethasone or cancer cell-conditioned medium, 4-hydroxyderricin protected the myosin heavy chain (MHC) degradation through suppressing expressions of MAFbx, MuRF-1 and myostatin." (PMID 31658768, 2019). "In this study, we will test the effect on muscle atrophy induced by cancer cachexia of IMB0901, a MSTN inhibitor." (PMID 30922397, 2019).
cancer (continued). "While the ubiquitin-proteasome system, autophagy-lysosome system, myostatin pathway, and PI3K/AKT pathway all play critical roles in muscle wasting, their involvement in cancer cachexia is not fully understood." (PMID 29069832, 2017). "Myostatin upregulation has been reported in different diseases with muscle wasting, such as HIV and cancer." (PMID 29036192, 2017). "In the cancer cachexia model, TGF-β family ligands such as myostatin bind to ActRIIB and lead to skeletal and cardiac muscle atrophy." (PMID 27029502, 2016). "ACVR2B is a high affinity activin type 2 receptor that mediates the intracellular signaling induced by myostatin, activin and GDF11 in skeletal tissue, whose inhibition attenuate cancer cachexia." (PMID 27330885, 2016). "Several well-established cachectic cytokines are elevated in the sera of cancer patients, including TNF-α, IL-6, and myostatin." (PMID 25972815, 2015). "Conversely, while myostatin signaling is commonly activated during cancer cachexia in rodents, it does not appear to be activated in the skeletal muscle of cachectic cancer patients." (PMID 39764565, 2025). "Many myostatin inhibitors failed in clinical trials in recent years; however, new potential candidates such as IMB0901 exhibited promising results in rescuing muscle atrophy in cancer cachexia." (PMID 35994202, 2022). "Although not always observed, high serum levels of activin and myostatin have been found in many cachectic cancer patients." (PMID 36078078, 2022). "In this study, we found that GRd protects against aging‐ and cancer‐induced skeletal muscle wasting by binding to STAT3, enhancing muscle function, and suppressing the expression of protein degradation factors such as MSTN, atrogin‐1, and MuRF‐1." (PMID 36127129, 2022). "We previously found that curcumin and gingerol potently inhibit MSTN and help suppress the expressions of advanced glycation end products and that of their receptor RAGE, which is also viewed as a potential therapeutic target for cancer cachexia." (PMID 33467209, 2021). "Therefore, there is an intricate signaling network with feed-forward and feedback loops comprising of NF-κB, PAX7, MyoD, myostatin, miR-486, and MMP-9 that regulate skeletal muscle homeostasis, which is disrupted in cancer." (PMID 31941005, 2020). "However, blocking tumor-derived cytokines (“tumorkines”), such as activin receptor (ACVR2) ligands (e.g., activins, myostatin and GDF11), by ACVR2 antagonism has attenuated muscle atrophy and improved survival in experimental cancer." (PMID 32365803, 2020). "In addition, the inhibition of myostatin alone or myostatin and GDF11 by neutralizing antibodies has attenuated cancer cachexia in vivo and muscle atrophy in vitro." (PMID 32365803, 2020). "Regarding muscle wasting in cancer cachexia, studies on patients with lung, colorectal and medullary thyroid cancer demonstrated that plasma myostatin concentration was decreased in patients with cancer cachexia compared to non-cachectic patients." (PMID 32796600, 2020). "Various factors, including PIF (tumor-derived factor), myostatin (skeletal muscle-derived factor), and cytokines, such as TNF-α and IL-6, can facilitate skeletal muscle depletion by inhibiting the PI3K/Akt signaling in cancer cachexia." (PMID 30754663, 2019). "The myostatin-activin-SMAD cascade has been shown to activate FOXO3a, a crucial activator of muscle-atrophy-related gene expression; ActRIIB antagonism suffices to revert muscle wasting and prolong survival in animals affected by cancer cachexia." (PMID 31068826, 2019). "As a dual MSTN inhibitor, IMB0901 could alleviate cancer cachexia by inhibiting muscle atrophy, via the reduction of ubiquitin-mediated proteolysis and the elevation of protein synthesis." (PMID 30922397, 2019). "The relationship between MSTN and cancer has not been fully elucidated, and there is even much controversy." (PMID 30922397, 2019).